CDK4 (cyclin dependent kinase 4)
Diseases named in the same sentence as CDK4 in open-access papers (continued):
Sharing a sentence is not in itself a finding about the gene and the disease.
tumor (continued). "In contrast, our findings show that copanlisib suppresses tumor growth in HCC cells mainly by triggering a G1 cell cycle arrest by inhibiting the cyclin D1/CDK4/CDK6 axis, without causing apoptosis." (PMID 30962952, 2019). "The inhibition of CDK4/6 results in the accumulation of the unphosphorylated form of the RB1 tumor suppressor, and this is the main mechanism responsible for cell proliferation arrest and for the global epigenetic reconfiguration of chromatin characteristic of senescent cells." (PMID 30692638, 2019). "It will be important to determine whether combined suppression of WNT and CDK4 could provide potent tumor responses in vivo and as an effective combination with current immune checkpoint inhibitors." (PMID 31891587, 2019). "In addition, HOTAIR also regulates the expression of P27, CylinD1 and CDK4 to promote the transition of tumor cells from G1 phase to S phase to inhibit the apoptosis through non-epigenetic mechanism or other indirect regulatory mechanisms." (PMID 31882666, 2019). "CDK4/6 inhibitors significantly suppress the PDX tumor growth with abnormal CDK4 pathway." (PMID 31358010, 2019). "Hotspot mutations in the ER ligand-binding domain (LBD), such as the D538G and Y537S, can provide tumor cells a growth advantage, suggesting that these ESR1 mutations, to an extent, may display innate resistance to CDK4/6 inhibitors." (PMID 31852484, 2019). "The CDK4 IHC results also indicated that CDK4 expression was suppressed with tumor reduction." (PMID 30808351, 2019). "Moreover, combining an inhibitor of the phosphoinositide 3-kinase (PI3K) pathway or of cyclin-dependent kinase-4/6 (CDK4/6) with AZD9496 led to an enhanced tumour inhibitory effect." (PMID 30555156, 2019). "We hypothesized that in addition to growth arrest, the inhibition of CDK4/6 reduces the angiogenic potential of the tumor cells which accounts for the strong inhibition of tumor growth." (PMID 30858922, 2019). "Accordingly, we speculate that specific inhibition of cyclin D1/CDK4 activity may produce clinical benefits for GC patients who have elevated expression of cyclin D1 and CDK4 in their tumours." (PMID 30714150, 2019). "Wt RB tumor suppressive function can be impaired by cyclin D/CDK4/6-mediated phosphorylation." (PMID 30349650, 2018). "Moreover, to examine the effect of DOT1L on tumor growth in vivo, hTERT/p53DD/CDK4(R24C)/BRAFV600E DOT1L-depleted melanocytes were inoculated subcutaneously into each flank of nude mice." (PMID 29343685, 2018). "As CDK4 expression could be regulated by miR-885-3p in vitro, we next determined its levels in mice tumor tissues." (PMID 29789536, 2018). "Our data suggest that CDH18 and a deeper understanding of SAGA might also predict if cell lines or a patient’s tumor would be innately resistant or clinically sensitive to CDK4/6 inhibitors." (PMID 29789718, 2018). "Indeed, evidence has been provided in several studies that treatment of epithelial cells in vitro or in vivo with cyclin D/CDK4/6 inhibitors results in cellular senescence and tumor suppression." (PMID 29309421, 2018). "This argued that targeting both MDM2 and CDK4 should yield synergistic tumor cell killing." (PMID 30206211, 2018). "The role of RB in apoptosis is far less explored, but recent interest in CDK4/6 inhibitors which rely on RB tumor suppressive function and induce an apoptotic response, has revealed that the mechanism is complex, but has been observed in different cellular contexts." (PMID 30349650, 2018). "Additionally, treatment with a CDK4/6 inhibitor and an anti-PD-1 antibody resulted in tumor regression and improved survival in vivo." (PMID 29765155, 2018). "Although the combination of PI3K and CDK4/6 inhibitors overcomes intrinsic and adaptive resistance leading to tumor regressions in PIK3CA mutant xenografts, the molecular mechanism underlying the resistance of AKTi and the synergy seen on the PI3K inhibitors and CDK4/6 inhibitors remain elusive." (PMID 30518851, 2018).
tumor (continued). "Thus, either inhibition of CDK4/6 or loss-of-function mutations of SPOP led to increased levels of PD-L1 and reduced tumor-infiltrating lymphocytes." (PMID 29765155, 2018). "Cyclin D1, CDK4, c-Myc, and p27kip1 contribute to tumor growth by promoting cell cycle progression." (PMID 29614812, 2018). "CDK4/6 coordinates the cell cycle progression by reversible combination with cyclin D, and the bipartite complex of these elements phosphorylates pivotal tumor suppressors and transcription factors, contributing to cell cycle progression." (PMID 28438180, 2017). "Furthermore, genomic profiling shows that cell cycle regulators are altered in the majority of EGFR-amplified tumours and a combination of cyclin-dependent kinase 4/6 (CDK4/6) and EGFR inhibitors prevents the emergence of resistance in vitro and in vivo." (PMID 28059068, 2017). "Interestingly, a high transcript level of CDKN2A was consistently observed in all the tumor cell lines with CDK4 amplification and high levels of CDK4 transcript reported in Cosmic database." (PMID 28566333, 2017). "In addition to these cancers, CDK4/6 inhibition should be particularly actionable for tumours whose pathways hyper-activate CDK4/6." (PMID 28513565, 2017). "These facts may suggest redundancy among CDKs, and that selection of appropriate target groups for CDK4/6 inhibition relies on successful identification of the tumor type." (PMID 28474232, 2017). "Therefore, the CDK4 modification predictor might also be used to bring together two pieces of information required to decide on treatment with CDK4/6 inhibitors: the sensitivity of the tumor and whether it is at high risk and therefore requires dedicated drugs." (PMID 28566333, 2017). "Since CDK4/6 inhibitors re-sensitize PDX tumors to HER2-targeted therapies and delay tumor recurrence in vivo, CDK4/6 inhibitors may also re-sensitize resistant HER2+ human BRCs to EGFR/HER2 inhibition." (PMID 28533703, 2017). "We therefore explored whether a gene expression profile could serve as a surrogate assay that faithfully predicts tumor CDK4 modification profiles and hence responsiveness to CDK4 inhibitors." (PMID 28566333, 2017). "Next, we explored whether our tumor‐based prediction tool can predict CDK4 modification profiles and PD0332991 sensitivity when applied to the gene expression profiles acquired from RNA extracted from our panel of 20 cell lines (accession GSE87006)." (PMID 28566333, 2017). "Importantly, combined inhibition of BRAFV600E and CDK4/6 synergistically induces apoptosis in both naïve and resistant tumor cells, indicating that the mechanism of resistance to vemurafenib requires CDK4/6 pathway activation." (PMID 29156680, 2017). "Using gene expression data from cell lines and tumors treated with abemaciclib and palbociclib a composite signature of response to CDK4/6 inhibition was developed that included many genes that are individually required for tumor cell proliferation or viability." (PMID 28620137, 2017). "The wide range of tumor lines was chosen to determine if G1T38 could globally inhibit proliferation via CDK4/6." (PMID 28418845, 2017). "The Hsp90 inhibitor AT13387 could inhibit NPC C666-1 cell growth and induced cellular senescence with the downregulation of multiple Hsp90 client oncoproteins EGFR, AKT, CDK4, and significantly suppressed tumor formation in C666-1 NPC xenografts." (PMID 28157708, 2017). "Additionally, in vivo abemaciclib leads to a substantial reduction in tumor volume through downregulation of CDK4, CDK6, Cyclin D, Rb1, and E2F1 gene expression." (PMID 29245989, 2017).
tumor (continued). "In this work, we show that the Ccnd1·Cdk4 complex phosphorylates a subpopulation of Pxn present in membrane ruffles but not in FAs, which is functionally relevant in the control of cell spreading and invasion in both normal fibroblasts and tumour cells." (PMID 27181366, 2016). "As cancer stem cells are key to tumor development and tumor propagation, we hypothesized that CDK4 may play an important role in regulating BCSC stemness, tumor relapse and drug resistance." (PMID 27759034, 2016). "Futhermore, such accumulated signaling could yield rapid tumor growth with the cessation of CDK4/6 inhibitory treatment." (PMID 27564114, 2016). "Furthermore, data from assays revealed that miR-486-5p significantly suppressed NSCLC tumor growth and cell cycle by targeting CDK4." (PMID 27049724, 2016). "Indeed, neither homozygous deletion/mutation of p107 and p130 nor mutation/copy number variations of upstream factors like p16INK4A, CDK4 or Cyclin D – which are common features of many tumor types – have been described." (PMID 27121059, 2016). "Reconstitution of either cyclin D1 or CDK4 in Tspan5-overexpressing GC cells rescues the inhibitory phenotype produced by Tspan5, suggesting that cyclin D1/CDK4 play a dominant role in mediating the suppression of tumour growth by Tspan5 in GC." (PMID 27223087, 2016). "This suggests that palbociclib or other CDK4/6 inhibitors could be used therapeutically to target multiple tumor types that rely on MEG3 regulated pathways for growth." (PMID 27832204, 2016). "In addition, the existence of a Ccnd1·Cdk4-Pxn-Rac1 axis helps explain the invasive properties of tumours overexpressing Ccnd1." (PMID 27181366, 2016). "Mechanistically, Tspan5 suppresses the tumour growth through regulating the cell cycle transition from G1-S phase by increasing the expression of p27 and p15 and decreasing the expression of cyclin D1, CDK4, pRB and E2F1." (PMID 27223087, 2016). "This was true for Ccnd1−/− fibroblasts, R3327-5′A tumour cells wherein Ccnd1 was knocked down with RNA interference, or Ccnd1+/+ fibroblasts treated with 2 μM Palbociclib, a specific inhibitor of Ccnd1·Cdk4." (PMID 27181366, 2016). "Thus, functional pRb and p16INK4a can serve as tumor suppressors, while cyclin D and CDK4/6 promote proliferation." (PMID 29263893, 2016). "Similar to the results in the Lovo cell line xenograft model, the combination of MEK and CDK4/6 inhibitors yielded significantly greater tumor growth inhibition in the PDX model compared to vehicle-treated controls or treatment with monotherapy of each drug alone." (PMID 27167191, 2016). "Furthermore, injection of HepG2 cells transfected with CDK4 WT/PRMT5 also resulted in a larger tumor width and tumor weight than those with CDK4 R24A/PRMT5." (PMID 27708221, 2016). "Similarly, Cdk4 was expressed in 16.4% of Brg1-negative tumor cells and in 90% of Brg1-positive tumor cells; this difference was also statistically significant (p=3.6E-6)." (PMID 28105458, 2016). "Collectively, these data support the hypothesis that the combination of MEK and CDK4/6 inhibitors induces tumor regression via the cooperative induction of cell cycle arrest, and that Ki67 and pS6 may serve as surrogates for combined target engagement." (PMID 27167191, 2016). "Our data reinforce the importance of these inhibitors in cancer therapy suggesting that the inactivation of Cyclin D·Cdk4,6 not only should produce tumour regression, as expected from its role in cell proliferation, but should restrict tumour spreading and metastasis as well." (PMID 27181366, 2016). "Studies have shown that downregulation of p16 gene expression resulted in the loss of its inhibitory effects on CDK4/CDK6, which in turn may lead to malignant, abnormal cell proliferation and accelerated tumor development." (PMID 27199504, 2016). "In conclusion, the interaction between PRMT5 and CDK4 rendered a tumor-promoting effect." (PMID 27708221, 2016).
tumor (continued). "Our results suggested that the weak binding of CDK4 R24A with PRMT5 inhibited HCC tumor growth." (PMID 27708221, 2016). "Moreover, the expression levels of the cell cycle G0/G1 regulatory protein CDK4 was significantly lower in tumor xenografts from treated mice than in tumor xenografts from control mice." (PMID 26525771, 2015). "Indeed, several CDK4/6 inhibitors have shown promising antitumor activity in experimental systems, and are presently under clinical evaluation for different tumor types." (PMID 26431489, 2015). "In most human tumours, the cell cycle regulators Cdk4/6-cyclinD are overactive." (PMID 25562820, 2015). "CDK4/6 and cyclin D play a key role in progression from G1 to S phase of the cell cycle through phosphorylation of the retinoblastoma protein (Rb), which inactivates Rb function as a tumor suppressor." (PMID 27648347, 2015). "In contrast, specific CDK inhibitors should provide selectivity and reduced toxicity because tumor cells may be selectively dependent on a certain pathway such as the cyclin D/CDK4/6/Rb pathway." (PMID 25914884, 2015). "This interpretation may have prognostic value since adjacent non-tumor mammary tissue from DMBA-treated animals had also increased expression of the proliferation markers Cdk4 and Ccnd1 (cyclin D1)." (PMID 26715507, 2015). "In tumor cells inhibiting CDK4 can induce senescence or quiescence depending on the cell type." (PMID 25803170, 2015). "Very little is known about whether genomic alterations in CDK4 can predict the tumor response to CDK inhibitors." (PMID 26528855, 2015). "Additionally, survival probabilities were significantly lower in tumor with high expression of cdk2 (p = 0.006), cdk4 (p = 0.003) or cdk6 (p = 0.045)." (PMID 26029996, 2015). "Such tumors rely on kinase activity of cyclin D1, and tumor growth could be abrogated not only by inactivation of cyclin D1 but also by CDK4/6 inhibition." (PMID 25940700, 2015). "To better understand the importance of RB1 activity in HPV-negative SCCHN, we investigated the prognostic value of inhibitory CDK4/6 phosphorylation of RB1 on threonine 356 (T356) in archival HPV-negative tumor specimens from patients who underwent surgical resection and adjuvant radiation." (PMID 26265441, 2015). "Furthermore, targeting CDK4 alleles in advanced tumours of this KRAS-mutant model induced senescence and prevented tumour progression, thereby highlighting the pharmacological importance of CDK4 for therapeutic strategies." (PMID 25625291, 2015). "Furthermore, the discovery of a synthetic lethal interaction between K-Ras oncogenes and CDK4 in a mouse tumour model of NSCLC revealed that KRAS-driven NSCLC is particularly dependent on CDK4." (PMID 25625291, 2015). "However, the presence of two variants both amplifying the same pathway formed the most compelling narrative for a driver pathway in this tumor, ultimately forming the basis for our treatment recommendation to start a CDK4/6 inhibitor." (PMID 26038725, 2015). "No completed study has demonstrated that activating CDK4 mutations affect the sensitivity of tumors or tumor cells to CDK inhibitors independently of 12q13-15 amplification." (PMID 26528855, 2015). "However, in PC-3 tumour biopsies, reduction in CDK4 levels were much more prominent in ACA stand alone treated, rhAFP/ACA ratio 1:3 and ratio 1:5 treated groups." (PMID 26158863, 2015). "Numb ablation by siRNA in vitro could inhibit tumor cell proliferation by downregulating CDK4 and SKP2 and upregulating p21 expression, and enhancing the apoptotic potential by upregulating BAK." (PMID 26165304, 2015). "Given our results in C. elegans, we wondered whether human tumour cells require CDK4/6-cyclin D activity to counteract APC/CFZR1." (PMID 25562820, 2015).
tumor (continued). "SST0116CL1 induced a relevant decrease of the protein levels of three typical client proteins (c-MET, AKT and CDK4) in GTL-16 tumor lysates and, at the same time, significantly increased the expression levels of the chaperone Hsp70, thus confirming that inhibition of Hsp90 function was achieved." (PMID 25096516, 2014). "This notion was reinforced when tumor cells expressing wild-type Rb were found to have genetic and epigenetic alterations of the p16 tumor suppressor gene or oncogenic expression of cyclin D1, D2, D3, Cdk4, and Cdk6 genes, which became known as the ‘p16-cyclin D-Rb’ pathway." (PMID 24876129, 2014). "The most significant correlation found earlier for PHD3 was with a low tumor grade (P = 0.000), while interestingly, there was a tendency for high CDK4 expression to correlate with a high tumor grade, supporting the identified inverse relation between these factors." (PMID 23336272, 2013). "This possibility is supported by the fact that many studies have recently demonstrated that tumours which are most sensitive to Cdk4/6 inhibitors are proficient for Rb, suggesting that these kinases drive tumour proliferation in the context of wild-type Rb activity." (PMID 23950948, 2013). "Tumour cell proliferation may therefore be particularly sensitive to selective inhibition of CDK4/6." (PMID 21610706, 2011). "Erk1/2 inhibitor pretreatment or incubation prevents this MICA decrease, while up-regulating key cell cycle related molecules such as CDK2, CDK4 and Cyclin D1, as well as apoptosis related molecules making resistant tumor cells now vulnerable to γδ T cell-mediated lysis." (PMID 21935360, 2011). "CDK4/cyclin D complexes and other Ras-related kinases modulate the phosphorylation of SMAD3, and this modulation of SMAD3 causes its downstream signaling to change from tumor suppressive to oncogenic." (PMID 20676395, 2010). "The results are important prerequisites for the design of in vivo biodistribution and imaging studies to further support our hypothesis that radiolabeled Cdk4 inhibitors are suitable radiotracers for tumor imaging by means of PET." (PMID 19551155, 2009). "We hypothesized that appropriately radiolabeled Cdk4 inhibitors are suitable probes for tumor imaging and may be helpful studying cell proliferation processes in vivo by positron emission tomography." (PMID 19551155, 2009). "If continued activation of CDK4/6 is required for tumor proliferation and survival, such drugs may have significant clinical use." (PMID 18764945, 2008). "This is unexpected as one might predict that reduced levels of p16 would result in deregulated activation of cyclin-dependent kinase 4/6 resulting in uncontrolled cell-cycle transition through the Rb pathway, leading to a higher tumour growth rate." (PMID 17533400, 2007). "The cell cycle regulators, such as ER-α, the ER-α linked cyclin D1, cyclin-dependent kinase 4 (cdk4), and proliferating cell nuclear antigen (PCNA), all followed this pattern of high in tumor tissues, intermediate in tumor-surrounding livers and low in control liver." (PMID 16507464, 2006). "However, highly elevated CDK4 mRNA levels, compared with that seen in a panel of normal tissues, were observed in 76% of the tumours, accompanied in 71% of the cases by high expression of the CCND1 cyclin activator." (PMID 8611425, 1996). "Second, as indications for certain adjuvant therapies rely upon high-risk anatomic features including nodal positivity, patients with ILC may be deemed ineligible for treatment such as CDK4/6 inhibitors, as they are less likely to have other tumor features like high grade or high Ki67." (PMID 41467111, 2026).